ADIPOQ (adiponectin, C1Q and collagen domain containing)
Diseases named in the same sentence as ADIPOQ in open-access papers (continued):
Sharing a sentence is not in itself a finding about the gene and the disease.
Insulin resistance (continued). "Literature data suggest that in humans, the plasma ADIPOQ concentration negatively correlates with body mass index and insulin resistance and is lower in patients with type 2 diabetes and PCOS." (PMID 37626836, 2023). "ADIPOQ is a precursor hormone that is known to play a crucial role in protecting against insulin resistance and atherosclerosis." (PMID 36100892, 2022). "Insulin resistance (IR) plays a major role in the pathogenesis of T2DM, and ADIPOQ participates in the process of insulin resistance." (PMID 33091065, 2020). "Nevertheless, more translational analyses using AD models are needed to authenticate the neuroprotective role of AdipoQ as therapeutic interventions to halt brain insulin resistance in AD." (PMID 33584324, 2020). "Unlike levels of other adipokines, those of adiponectin (also known as Acrp30, AdipoQ, and GBP28) decrease in obesity-induced metabolic disorders, including insulin resistance." (PMID 28870184, 2017). "This genomic region has revealed strong linkage to insulin resistance and T2D, suggesting that ADIPOQ is a candidate gene for T2D." (PMID 25909078, 2015). "PPARG2 has been shown to increase transcription of the ADIPOQ gene and many other genes that are involved in the pathogenesis of insulin resistance." (PMID 23285067, 2012). "ADIPOQ also characterizes the pathogenesis of the insulin resistance that is a common trait of AD patients." (PMID 21726470, 2011). "Conversely, insulin resistance associated genetic variants of PPARG, ADIPOQ and ENPP1 were found to be only associated in obese subjects." (PMID 18498634, 2008). "Alternatively, there may be undiscovered SNPs in the ADIPOQ gene or other genes that have biological effects on insulin resistance." (PMID 39290095, 2024). "The downregulated molecules include DEPs improving insulin resistance, in particular, ADIPOQ." (PMID 38672154, 2024). "Previous studies have proposed that ADIPOQ has a variety of biological functions, including improving animal reproductive performance, modulating the inflammatory response, improving glucose lipid metabolism disorders, and relieving insulin resistance." (PMID 36009866, 2022). "Reduction in expression of Insr, Irs1, and AdipoQ may possibly contribute to the severe insulin resistance that developed after a second exposure to HFD." (PMID 31234301, 2019). "The expression of AdipoQ is decreased when there is insulin resistance." (PMID 29434026, 2018). "Indeed, our group was the first to report that the rs1501299 SNP of the ADIPOQ gene is associated with polycystic ovarian syndrome (PCOS), a disease strongly linked with insulin resistance." (PMID 30360393, 2018). "By contrast, expression of the ADIPOQ gene encoding adiponectin, another adipokine inversely related to obesity-associated insulin resistance, did not significantly vary (FDR = 0.37)." (PMID 25938420, 2015). "Variants in the ADIPOQ gene accounted for <5% of the variation in serum adiponectin and genetic variants in ADIPOQ and its receptors does not appear to contribute to the risk of insulin resistance or metabolic syndrome." (PMID 23351195, 2013). "Also called gelatin-binding protein-28 (GBP28), AdipoQ, ACRP30 or apM1, adiponectin is considered a link between obesity, insulin resistance and diabetes." (PMID 16570048, 2006). "However, genetic variation in ADIPOQ and its receptors does not appear to contribute to the risk of insulin resistance or metabolic syndrome but did for type 2 diabetes in a European-Australian population." (PMID 23351195, 2013). "Interestingly, the variants in PPARG, ADIPOQ, and ENPP1, which elevate risk in obese populations, have been categorized as acting on insulin resistance while the TCF7L2 variant elevating risk in lean populations has been categorized as acting on insulin secretion." (PMID 18498634, 2008).
Insulin resistance (continued). "ADIPOQ and TNFA increase insulin sensitivity and insulin resistance, respectively, through modulation of phosphorylation and activation of IRS-1 (a molecule determining insulin sensitivity2930,31." (PMID 41193585, 2025). "Inflammation, renin-angiotensin system-sympathetic nervous system activation and insulin resistance, endothelial dysfunction Shared genes among hypertension, NAFLD, fibrosis, and inflammation include LEP, ADIPOQ, AHR and TGFB1." (PMID 37664266, 2023). "Altered secretions of adipokines such as adiponectin (ADIPOQ), leptin (LEP) and resistin (RETN) by adipose tissues is one of the important contributory factors to insulin resistance, cardiovascular diseases and metabolic disorders." (PMID 32695266, 2020). "Genome loci based data and population study support that highly connected genes, like ADIPOQ, MAPK3, PLCG1 and APPL1 in the database, play an important role in insulin resistance development." (PMID 29201145, 2017). "The persistent downregulation of ADIPOQ in STEMI patients suggests impaired adipose tissue function and dysregulated adipokine secretion, contributing to systemic inflammation, insulin resistance, and endothelial dysfunction observed in acute myocardial infarction." (PMID 39513871, 2024). "Conversely, the low expression of ADIPOQ in the INS_K group could contribute to their lower SREBF1 expression and more severe insulin resistance." (PMID 39881718, 2024). "Previous studies in Saudi Arabia using genetic variants of ADIPOQ have examined coronary artery disease (CAD) in T2DM, MetS, and PCOS and insulin resistance in non-diabetic Saudi women, as well as T2DM and colon cancer." (PMID 37238960, 2023). "A meta-analysis showed that the genetic variation in ADIPOQ named T45G, is not related to insulin resistance or blood glucose." (PMID 36114448, 2022). "Additionally, different studies have proposed potential DNA methylation biomarkers in relation to plasma insulin levels, insulin secretion and insulin resistance such as those located in PPARGC1A, HTR2A, LY86, TFAM, GIPR, ADIPOQ, and IGFBP3 genes." (PMID 31208038, 2019).
diabetes (57 papers, 2010 to 2025). "Adiponectin, a protein encoded by the ADIPOQ gene situated in the chromosomal region 3q27, plays a significant role in diabetes development." (PMID 40454209, 2025). "Polymorphisms in ADIPOQ, which codes for adiponectin, have been associated with diabetes and metabolic syndrome in multiple populations." (PMID 37831337, 2024). "Recently, a family harboring a 10-nucleotide deletion mutation in ADIPOQ was reported to co-segregate with diabetes and end-stage renal disease." (PMID 38674417, 2024). "These SNPs within ADIPOQ play a crucial role in evaluating the link between common genetic variants, adiponectin levels, and the risk of diabetes." (PMID 38004353, 2023). "We identified a family harboring a 10-nucleotide deletion mutation in ADIPOQ that cosegregates with diabetes and end-stage renal disease." (PMID 35869090, 2022). "In summary, we identified the first multigenerational family with a protein truncating mutation in ADIPOQ, diabetes, and end-stage renal disease." (PMID 35869090, 2022). "We report the identification of a rare truncating mutation in ADIPOQ in a multigenerational family enriched for diabetes and end-stage renal disease." (PMID 35869090, 2022). "Here, we describe the first multigenerational family with a protein-truncating mutation in ADIPOQ (p.Gly93GlufsTer73), diabetes, and end-stage renal disease." (PMID 35869090, 2022). "The concentration of AdipoQ in the plasma was positively associated with total fiber intake and cereal fiber intake in diabetes-free women through a cross-sectional analysis." (PMID 34684387, 2021). "Various single nucleotide polymorphisms (SNPs) of the ADIPOQ gene are associated with the development of type 2 diabetes mellitus (T2D), metabolic syndrome, and cardiovascular diseases." (PMID 31561637, 2019). "The genetic variant rs17300539 in ADIPOQ gene was studied in four european studies, all involving type 1 diabetes mellitus." (PMID 25280384, 2014). "PPAR-γ is a transcriptional regulator which directly interacts with the ADIPOQ promoter, both of them are closely associated with IR, MetS and diabetes mellitus." (PMID 21513558, 2011). "However, to our knowledge, this is the first finding that ADIPOQ rs182052 and rs1501299 polymorphisms have respective significant additive and multiplicative interactions with diabetes to enhance the risk of CKD." (PMID 37175838, 2023). "There is an association between ADIPOQ polymorphisms and type 2 diabetes mellitus." (PMID 33918360, 2021). "The present study aimed to determine whether the polymorphisms at rs2241766 and rs1501299 on the ADIPOQ gene were related to the susceptibility of type 2 diabetes mellitus (T2DM)." (PMID 33091065, 2020). "Leptin acted as a diabetes-specific regulator of mitochondrial crosstalk, whereas ADIPOQ served that role in relation to sarcopenia, pointing to disease-tailored endocrine wiring." (PMID 40869253, 2025). "The divergence of LEP (diabetes-specific) versus AdipoQ (sarcopenia-specific) further emphasizes distinct endocrine wiring that tailors adipokine–mitochondria crosstalk to each disease’s metabolic context." (PMID 40869253, 2025). "Later, it was observed in several studies that ADIPOQ played an essential role in patients with post-transplant diabetes mellitus." (PMID 37372431, 2023). "The analysis showed that five SNPs were associated with diabetes: rs1024611 at the CCL2 gene locus, rs6749704 at CCL20, rs333 at CCR5, rs17366743 at ADIPOQ, and rs114758349 at TCF7L2." (PMID 36674502, 2023). "The association between ADIPOQ polymorphisms and CKD was analyzed after stratification by medical history, such as diabetes and hypertension, blood cadmium and lead, plasma selenium, and total urinary arsenic." (PMID 37175838, 2023). "Adiponectin (ADIPOQ) regulates fatty acid oxidation, glucose uptake, and glycogenesis, which is related to the pathogenesis of diabetes." (PMID 33091065, 2020).
diabetes (continued). "ADIPOQ is expressed and secreted completely from adipocytes and has been identified as a cytokine with anti‐diabetes, anti‐inflammatory, and anti‐atherosclerosis properties." (PMID 30838812, 2019). "In conclusion, offspring of women with diabetes in pregnancy exhibit increased ADIPOQ DNA methylation and decreased ADIPOQ and RETN gene expression in SAT." (PMID 28413567, 2017). "Growing evidence links environmental exposure to hexachlorocyclohexanes (HCHs) to the risk of type 2 diabetes mellitus (T2DM), and ADIPOQ that encodes adiponectin is considered as an important gene for T2DM." (PMID 27883041, 2016). "We then examined whether the expression of HMGA2, PPARG, ADIPOQ and IL6 was associated with diabetes remission." (PMID 40740163, 2025). "Finally, the divergent behavior of leptin positively correlated only in diabetes, while AdipoQ was only positively correlated in sarcopenia; this points to pathology-specific regulatory axes layered atop this shared network." (PMID 40869253, 2025). "The data suggested that ENSG00000226482 may upregulate the ADIPOQ expression, active multiple signaling pathways, abnormal lipid metabolism, diabetes, and atherosclerosis, leading to acute ischemic stroke." (PMID 33327229, 2020). "Large-scale genome-wide association studies identified loci for type 2 diabetes mellitus (T2DM), including adiponectin (ADIPOQ) gene and transcription factor 7-like 2 (TCF7L2), but few studies clarified the effect of genetic polymorphisms of ADIPOQ and TCF7L2 on risk of T2DM." (PMID 25121131, 2014). "The best model for predicting liver inflammation (METAVIR grade 2–3) comprised CXCL10, TIMP1 and APRI (AUROC = 0.798); whereas the best model for predicting steatohepatitis incorporated IL8, ADIPOQ, MMP2, MMP7, age, BMI and diabetes (AUROC = 0.857)." (PMID 27861569, 2016). "Additionally, the tissue-specific expression of adipokines such as AdipoQ in sarcopenia and LEP in diabetes further underscores the pathology-specific regulatory mechanisms that modulate mitochondrial function through endocrine signaling." (PMID 40869253, 2025). "Collectively, this panoramic view articulates a core mitochondrial dysfunction signature common to sarcopenia and diabetes, a classical adipokine–mitochondria support network, a novel counter-regulatory myokine/adipokine module, and tissue- and disease-specific modifiers (NNMT, LEP, and AdipoQ)." (PMID 40869253, 2025). "There are also other novel targets for diabetes mellitus control that could be exploited, such as GPCR 119, GPER, 11β-hydroxysteroid dehydrogenase 1, Vaspin, Metrnl, PEDF, Fetuin-A, ACRP 30(AdipoQ), Visfatin, Melatonin, GIP, GPCR." (PMID 36782201, 2023).
type 2 diabetes mellitus (57 papers, 2009 to 2025). A type of diabetes mellitus that is characterized by insulin resistance or desensitization and increased blood glucose levels. "ADIPOQ gene polymorphisms are related to adiponectin levels, insulin resistance, and metabolic diseases such as diabetes mellitus type II (DMT2)." (PMID 39449424, 2024). "ADIPOQ gene, which is located on chromosome 3q27, the region that was proposed to be a “susceptibility locus for type 2 diabetes” by the recent human genome-wide scans, encodes for the adipose tissue-derived adiponectin hormone." (PMID 37953238, 2023). "ADIPOQ gene polymorphisms rs10937273, rs1501299, rs182052, rs2241767, and rs266729 were associated with type 2 diabetes." (PMID 32685510, 2020). "We investigated the potential association between the ADIPOQ gene polymorphism and metabolic parameters in type 2 diabetic patients." (PMID 27942572, 2016). "The adipocyte-derived hormone adiponectin (also known as 30-kDa adipocyte complement-related protein; Acrp30) has been mapped to a susceptibility locus for type 2 diabetes within the AdipoQ gene." (PMID 26625115, 2015). "Little research has been done on the association of ADIPOQ gene on type 2 diabetes, plasma adiponectin, blood glucose, HOMA-IR and body mass index (BMI) in African Americans." (PMID 26699120, 2015). "In addition, Peroxisome proliferator-activated receptor gamma (PPARγ), which regulates transcription of ADIPOQ gene, is associated with increased adiponectin levels and a reduced risk of type 2 diabetes." (PMID 38674417, 2024). "ADIPOQ could increase insulin sensitivity and its circulating levels have been found inversely associated with the risk of type 2 diabetes." (PMID 34702323, 2021). "SNPs in ADIPOQ have also been reported to be associated with type 2 diabetes." (PMID 27703473, 2016). "Metabolic syndromes including type 2 diabetes and excess fat deposition could be caused by the differential expressions of ADIPOQ and LEP genes in males and females as a result of the respective SNPs." (PMID 27703473, 2016). "Several possible reasons may account for the difference between Asians and Caucasians in the association of the ADIPOQ gene +45T>G polymorphism with type 2 diabetes." (PMID 25561226, 2014). "For example, the pathway of the disease of type II diabetes mellitus, is correlated to tobacco smoking, and the genes involved are ADIPOQ, PIK3CA, and SLC2A2." (PMID 32455963, 2020). "Sixty-four tagging single nucleotide polymorphisms in ADIPOQ, ADIPOR1 and ADIPOR2 were genotyped in two general population cohorts consisting of 2,355 subjects, and one cohort of 967 subjects with type 2 diabetes." (PMID 23351195, 2013). "The identified genes were involved in processes such as protein localization (ENSSSCG00000041063, ADIPOQ, ABCC8), enzyme-linked receptor protein signaling pathway (PLCE1, ADIPOQ), organic substance transport (ENSSSCG00000041063, ADIPOQ, ABCC8), and type II diabetes mellitus (ADIPOQ, ABCC8)." (PMID 40819340, 2025). "Previous studies that did not include African Americans detected an association of ADIPOQ SNPs in the promoter region or in exons (exon 3) with morbid obesity and with type 2 diabetes." (PMID 26699120, 2015). "Variants in ADIPOQ, the gene encoding adiponectin, have been shown to influence serum adiponectin concentration, and along with variants in the adiponectin receptors (ADIPOR1 and ADIPOR2) have been implicated in metabolic syndrome and type 2 diabetes." (PMID 23351195, 2013). "All genes except ADIPOQ in Cluster 1 and Cluster 3 were upregulated in the NFIL3-high group and involved in IL-17 signaling pathways and the type II diabetes mellitus pathway." (PMID 36439145, 2022).